CENPU (centromere protein U)
Diseases named in the same sentence as CENPU in open-access papers (continued):
Sharing a sentence is not in itself a finding about the gene and the disease.
tumor (15 papers, 2018 to 2025). "We conducted a pan-cancer analysis to investigate the immune effects of L1 ASP associated genes, specifically MCM2 and CENPU, in the tumor immune microenvironment." (PMID 37723560, 2023). "Moreover, we observed that the expression specificity of certain L1 ASP-associated genes, such as CENPU, was associated with the prognosis of tumor patients in various tumors." (PMID 37723560, 2023). "Additionally, univariate and multivariate analyses showed that TMN stage, tumor depth, distant metastasis, and CENPU expression can be used as independent risk factors for HCC." (PMID 34957303, 2021). "Our SCNA analysis demonstrated that CENPU was deleted in the post-treatment tumor samples in our cohort and that pathways related to cell cycle progression were downregulated in the RNA-seq data." (PMID 38217005, 2024). "Previous studies have shown that CENPU participates in tumor proliferation and metastasis, and the results of our study are consistent with these findings." (PMID 37723560, 2023). "Studies have revealed that CENPU expression is highly expressed in NSCLC tissues and that CENPU knockdown represses tumor proliferation and metastasis in NSCLC cells by regulating the Wnt/β-catenin signaling pathway." (PMID 34957303, 2021). "CENPU has been found to be overexpressed in a variety of tumor tissues and cancer phenotypes, and high expression level of CENPU predicts poor prognosis in many cancer phenotypes." (PMID 34872447, 2021). "Next, we conducted an analysis of CENPU expression in tissue samples deposited in The Cancer Genome Atlas (TCGA) and Clinical Proteomic Tumor Analysis Consortium (CPTAC) databases by using the online database UALCAN." (PMID 33902008, 2021). "The analysis showed that high mRNA levels of CENPL, CENPQ, CENPR, and CENPU were significantly correlated with tumor stages (p < 0.01)." (PMID 34457090, 2021). "We found that the mRNA levels of 4 out of 15 centromere proteins (CENPL, CENPQ, CENPR, and CENPU) were significantly higher in HCC than in normal tissues, and their mRNA levels were associated with the tumor stages (p values < 0.01)." (PMID 34457090, 2021). "In the current study, we conducted in vitro assays to investigate the effect of CENPU on tumor development." (PMID 34957303, 2021). "Knockdown of CENPU suppressed the tumor growth with significantly decreased tumor volume and tumor weight." (PMID 34872447, 2021). "Hub genes CENPU and MCM2 are expected to be new tumor diagnostic markers and therapeutic targets." (PMID 37723560, 2023). "Additionally, IHC staining showed decreased expression of Ki-67, cyclin D1, cyclin E1, and E2F1 in sh-CENPU-treated Huh-7 xenograft tumours." (PMID 35844791, 2022). "In brief, CENPU enhanced the tumour formation, growth, and metastasis of HCC in vivo." (PMID 35844791, 2022). "The volume and weight of xenograft tumours decreased visibly following stable silencing of CENPU." (PMID 35844791, 2022). "In the last, the influence of CENPU on the tumor growth in vivo was investigated." (PMID 34872447, 2021). "The expression of Centromere Protein U (CENP-U) is closely related to tumor malignancy." (PMID 33833984, 2021). "CENPU is overexpressed in many cancer phenotypes, and regulates tumor development." (PMID 34872447, 2021). "However, overexpression of CENPU promotes proliferation of tumor cells through reduced activity of its transcription factor." (PMID 31281827, 2019). "Moreover, high expression of MCM2 and CENPU was also closely associated with tumor stemness in several tumors, including GBMLGG, CHOL, STAD, PAAD, LUSC, PRAD, etc., indicating their potential as key targets for tumor treatment." (PMID 37723560, 2023). "Through protein interaction network analysis, we discovered two hub genes, CENPU and MCM2, that play important roles in pan-cancer species and are closely related to tumor T staging and tumor stemness in pan-cancer." (PMID 37723560, 2023).
tumor (continued). "CENPU mRNA levels were also elevated in HCC specimens, according to qRT-PCR analysis of 80 pairs of HCC tumour and peritumour tissues." (PMID 35844791, 2022). "Then, we selected 4 CENPs (CENPL, CENPQ, CENPR, and CENPU) with high expression in HCC as shown in both the Oncomine and GEPIA databases to further analyze the relationship between mRNA levels and tumor stages." (PMID 34457090, 2021). "IHC assay revealed that knockdown of CENPU led to significantly deceased expression levels of CENPU, HMGB2 and ki-67 in tumor tissue." (PMID 34872447, 2021). "For example, Centromere Protein U (CENPU) enhances glycolysis and proliferation by upregulating High Mobility Group Box 2 (HMGB2), while CD73 is induced under hypoxia to boost glycolytic capacity and promote tumor growth." (PMID 41220952, 2025). "Overexpression of CENPU was significantly correlated with histologic grade (P = 0.002), tumor-node-metastasis (TMN) stage (P = 0.001), and tumor depth (P < 0.001), while overexpression of CENPU was not connected with age, sex, M, and N classification." (PMID 34957303, 2021). "We first investigated the CENPU transcript level in multiple tumour types and found that CENPU expression was increased in the tumour group in comparison to the corresponding nontumor group for the majority of tumour types." (PMID 35844791, 2022). "Seven pairs of tumor and adjacent non-tumorous tissues were selected to verify the expressions of the ZWINT, RRM2, NDC80, KIF4A, CEP55, CENPU, and CENPF genes." (PMID 35028418, 2022).
cancer (13 papers, 2018 to 2024). A tumor composed of atypical neoplastic, often pleomorphic cells that invade other tissues. "Meanwhile, CENPU and CENPK also existed in the core PPI network and were associated with cancer cell value-added and differentiation-related processes." (PMID 38919957, 2024). "Hub L1 ASP-associated genes CENPU and MCM2 showed a correlation with immune infiltration, clinical T stage, and cancer stemness in pan-cancer." (PMID 37723560, 2023). "For instance, the expression of CENPU, a gene involved in the proliferation and metastasis of various tumors, was found to be closely related to patient prognosis in 15 different types of cancer." (PMID 37723560, 2023). "CENPU is a novel transcriptional repressor that is related to various cancers." (PMID 35028418, 2022). "Downregulation of CENPU suppresses the proliferation and invasion of cancer cells." (PMID 34872447, 2021). "Centromere protein U (CENPU) has been found to be overexpressed in many types of cancer." (PMID 34872447, 2021). "We further demonstrated that the anti-cancer effect of CENPU exhibited a HMGB2-dependent manner." (PMID 34872447, 2021). "Knockdown of CENPU inhibits cancer cell proliferation and invasion." (PMID 34872447, 2021). "Accumulating evidence has indicated that CENPU is upregulated in several human cancers and may play a key role in cancer progression." (PMID 34957303, 2021). "Further the results showed that the anti-cancer effect of CENPU was HMGB2-dependent." (PMID 34872447, 2021). "Abnormal expression of centromere protein U (CENPU) is closely related to diverse human cancers." (PMID 34957303, 2021). "Suppression of CENPU expression inhibits cancer cell proliferation, migration, and invasion." (PMID 34872447, 2021). "Furthermore, the immunohistochemical staining results based on the HPA database revealed a significantly high positivity of the ZWINT, RRM2, NDC80, KIF4A, CEP55, CENPU, and CENPF genes in cancer tissues compared to adjacent normal tissues." (PMID 35028418, 2022).
infection (1 paper, 2023). The state of being infected such as from the introduction of a foreign agent such as serum, vaccine, antigenic substance or organism. "We noted a high level expression of RRM2, MYBL2, and some other genes such as GALNT14, CENPU, ACOXL, and U2 at 0 weeks during active phase of infection, which were downregulated at 8 weeks after therapy." (PMID 37434783, 2023).
CENPU also shares sentences with these, for which no sentence is quoted: cervical cancer (1 paper); colon cancer (1); ductal carcinoma in situ (1); esophageal cancer (1); Fanconi anemia (1); invasive breast carcinoma (1); lymph node metastasis (1); Lynch syndrome (1); meningioma (1); oligospermia (1); osteosarcoma (1); pancreatic cancer (1); rectal cancer (1); s sarcoma (1); stomach cancer (1).